MIR3609 (microRNA 3609)
Synonyms: hsa-mir-3609; mir-3609
Gene: MicroRNA gene on chromosome 7 (98,881,650 to 98,881,729, forward strand). Ensembl gene ENSG00000266019.
Diseases named in the same sentence as MIR3609 in open-access papers:
MIR3609 is named in the same sentence as 1 disease in open-access papers, as found by Europe PMC text mining. Sharing a sentence is not in itself a finding about the gene and the disease. The quoted sentences say what the papers report.
infection (1 paper, 2025). The state of being infected such as from the introduction of a foreign agent such as serum, vaccine, antigenic substance or organism. "In contrast, genes such as RNA5S9, RPL7B9, MIR3609, RPS3AP26, and RPL21P16 were commonly found among the top ten differentially expressed genes in both the 16-week post-infection (16wpi) and 24-week post-infection (24wpi) patient groups." (PMID 41141600, 2025).